LAMP2 (lysosome associated membrane protein 2)
Diseases named in the same sentence as LAMP2 in open-access papers (continued):
Sharing a sentence is not in itself a finding about the gene and the disease.
cancer (continued). "For instance, in neuroendocrine prostate cancer, knockdown of LAMP2 by siRNA induced an autophagy blockade and decreased both cancer cell proliferation and neuroendocrine markers." (PMID 38240686, 2024). "Although less studied compared to LAMP1 and LAMP2, LAMP5 overexpression is associated with lysosome repositioning to the cell periphery in mixed lineage leukemia, and the promotion of cancer stemness and EMT in gastric cancer." (PMID 38474423, 2024). "The downregulation of LAMP2 decreased the secretion of EVs and sensitized cells to the anti-cancer drug lenalidomide." (PMID 38474423, 2024). "Within the cancer landscape, studies have shown that LAMP2 plays a role in cell survival and disease progression." (PMID 38240686, 2024). "Taken together, these findings show that the expression of LAMP2 is significantly reduced in some cancers, and affects the cancer cell itself and the tumor microenvironment." (PMID 37986192, 2023). "All of this contrasted with the observations in other cancers such as colon (for LAMP-2) or breast (for AGTR1), which presented an increase in expression levels and consequently a decrease in MMP-2 levels." (PMID 36765855, 2023). "In turn, inhibition of LAMP-2 reverses macrophage activation, increasing tumor cytotoxicity and inhibiting cancer progression." (PMID 36830954, 2023). "The subcellular localization of LAMP2 in cancer cells indicated that it was predominantly expressed in cytoplasmic lipid droplets." (PMID 35530327, 2022). "Altered levels of CMA have been reported in a wide range of pathologies including many cancer types that upregulate CMA as part of the pro-tumorigenic phenotype, while in aging a decline is observed and associated with a decrease of LAMP-2 expression." (PMID 36010638, 2022). "To evaluate the relevance of LAMP2 to immunity in cancer progression, we explored the relationships between LAMP2 expression and immunoinhibitors, immunostimulators, chemokines, and receptors in human heterogeneous carcinomas based on TISIDB." (PMID 35530327, 2022). "Accumulating evidence indicates an important role of lysosomal-associated membrane protein 2 (LAMP2) in the progression and development of various cancers." (PMID 35530327, 2022). "In this study, our findings supplemented those of previous reports to indicate that LAMP2 has a potential as a new epigenetic biomarker and target that promotes the development and progression of the majority of malignant tumors." (PMID 35530327, 2022). "The TIMER database was used to analyze LAMP2 mRNA expression in 25 commonly occurring types of human cancer." (PMID 35530327, 2022). "Accumulating evidence indicates that lysosomes play an important part in various cancers; this has raised interest in the role of LAMP2 in cancer progression." (PMID 35530327, 2022). "In neuroendocrine prostate cancer, knockdown of LAMP2 by siRNA induced an autophagy blockade and decreased both cancer cell proliferation and neuroendocrine markers." (PMID 33718194, 2021). "These authors suggest that LAMP2 redistribution at the PM is an adaptive mechanism that allows cancer cells to survive in a harsh, acidic microenvironment by forming a protective glycocalyx that circumvents acid-induced proteolysis of the PM." (PMID 33718382, 2021). "Nevertheless, the sensitization to radiotherapy and chemotherapy by LAMP2 targeting should be investigated in other types of cancer cells." (PMID 33718194, 2021). "In the tumor area in which carcinoma cells are coupled with OC, we also observed LAMP2 staining in cancer cells, indicating that those areas that are characterized by the presence of actively resorbing OC were associated with acidifying carcinoma cells." (PMID 34124067, 2021). "Another example of the consequences of deregulated lysosomal exocytosis is that redistribution of LAMP1 and LAMP2 at the PM of cancer cells promotes tumor invasion and metastasis via the interaction of their glycan exposed domains with galectins and selectins." (PMID 33718382, 2021).
cancer (continued). "Although the expression level of LAMP2 seems to be different in various cancer types, several data suggest that LAMP2 is a potential target for cancer therapy in combination with conventional treatments." (PMID 33718194, 2021). "In some cancers, demethylation of normally methylated genes occurs (global hypomethylation), which leads to the activation of a given gene (e.g., LAMP2 in the present study)." (PMID 33322704, 2020). "Changes in LAMP2 gene expression in carcinogenesis are dependent on the type of cancer and its histopathological differentiation." (PMID 33322704, 2020). "In all of these examples, the increase in LAMP2 occurred in the early stages of the cancer and indicated a poor prognosis for the patient." (PMID 33322704, 2020). "Upregulation of Lamp2 in the plasma membrane is induced by chronic acidosis to protect cancer cells from acid-induced hydrolysis and to promote their survival via chaperone-mediated autophagy." (PMID 32117965, 2020). "Previous studies have found that chronic acidosis–induced Lamp2 overexpression in cancer cells confers plasma membrane resistance against acidosis-induced proteolysis." (PMID 32117965, 2020). "Analyzing the results, we can assume reduced methylation in the promoter regions of LAMP2 in cancer with respect to the control." (PMID 33322704, 2020). "Available research suggests that lysosome-associated membrane protein 2 (LAMP2), for instance, is a crucial protein that contributes to cancer cell survival under acidosis." (PMID 31906017, 2019). "LAMP2 contributes to resistance, as the so called lysosomal cell death induced by anti-cancer drugs is decreased when LAMP2 is overexpressed in fibroblasts." (PMID 30871022, 2019). "We used LAMP2 staining as a marker of the acidic microenvironment, which was confined to the carcinoma cells, as indicated by a complete overlapping with the cytokeratin signal (yellow color in the merged image of the second string)." (PMID 28903357, 2017). "IHC staining of cancer cell spheroids showed overexpression of LAMP2 at the approximate oxygen diffusion limit." (PMID 26658462, 2015). "As an important component of acid adaptation, LAMP2 expression at cell surface of acid-induced cancer cell can provide a novel therapeutic target." (PMID 26658462, 2015). "For LAMP1 and LAMP2 it has been previously established that their expression can relocalize to the plasma membrane in cancer cells." (PMID 23294542, 2013). "Confocal analysis revealed colocalization of GFP-LC3 and LAMP2 in cancer cells treated with siRNA against COPB2, suggesting fusion was not completely blocked by depletion of COPI." (PMID 22745748, 2012). "For example, in carcinoma cells, relevant glycoprotein ligands of galectin-1 were identified as lamp-1 and lamp-2, carcinoembryonic antigen, and the fibronectin receptor." (PMID 19898636, 2009). "To validate the in silico data, we investigated in vitro whether LAMP2 modulation influences the sensitivity of cancer cells to inhibitors of the de novo purine synthesis." (PMID 41381430, 2025). "The decrease in LAMP-2 transcriptional activity in subsequent stages of cancer advancement indicates the inhibition of chaperone-dependent autophagy, which suggests the accumulation of damaged proteins in the cell, which may lead to tumor progression." (PMID 36830954, 2023). "Therefore, further research at the molecular level is needed in this field, which will help determine the relationship of the LAMP-2 protein with cancer progression and identify signaling pathways contributing to the development of the disease." (PMID 36830954, 2023). "Ultimately, LAMP2-related studies and new targeted therapies may help to improve the poor prognosis of patients with esophageal and other cancers." (PMID 35530327, 2022).
cancer (continued). "In addition, LAMP2 expression on the plasma membrane promotes the adhesion of cancer cells to the extracellular matrix, basement membrane, and endothelium, as well as the migration potential of cancer cells during metastasis." (PMID 35530327, 2022). "In addition, LAMP2 expression was associated with certain clinicopathological parameters, prognosis, and immune infiltration in ESCA and the other types of cancer." (PMID 35530327, 2022). "The results verified the prognostic value of LAMP2 on a pan-cancer basis." (PMID 35530327, 2022). "Similarly, studies have confirmed that LAMP2 can promote cell migration and invasion in some types of cancers, including LUAD, LIHC, COAD, and PRAD." (PMID 35530327, 2022). "Moreover, we performed the pan-cancer analysis of LAMP2 to further analyze the role of LAMP2 in 25 commonly occurring types of human cancer." (PMID 35530327, 2022). "In conclusion, LAMP2 is highly expressed in the immune and molecular subtypes of some cancer types." (PMID 35530327, 2022). "Moreover, we analyzed the relationships between LAMP2 expression and prognostic value, different immune infiltration parameters, and different clinicopathological features in other human cancers." (PMID 35530327, 2022). "In addition, we analyzed the protein expression of LAMP2 across 10 cancer subtypes in CPTAC samples based on UALCAN data." (PMID 35530327, 2022). "LAMP2 (CD107b) is a highly glycosylated protein which is normally present in the lysosomal membranes and occasionally in cell membranes, known to regulate cell invasion and migration in several cancers." (PMID 33042286, 2020). "LAMP2 can protect lysosomal membranes from acidic proteolysis during cancer development." (PMID 31906017, 2019). "Additionally, high LAMP2 expression may also represent an intrinsic mechanism of resistance to inhibitors of purine synthesis in those cancer types in which LAMP2 is upregulated." (PMID 41381430, 2025). "Thus, the detection of LAMP2 on RBCs from metastatic BC patients may be related to impaired hematopoiesis, a phenomena frequently found on cancer patients." (PMID 36519745, 2022). "In addition, LAMP2 had a better reliability in the remaining cancers (0.7 < AUC < 0.9)." (PMID 35530327, 2022). "Therefore, whether LAMP2 could also be a pan-cancer molecular biomarker, especially in ESCA, is worth further study." (PMID 35530327, 2022). "Given the pivotal role of LAMP2 in lysosomal stability, targeting LAMP2 could be a strategy to destabilize lysosomes of cancer cells and potentiate the efficacy of lysosomotropic agents, which accumulates into lysosomes and damage them, resulting in LMP and activation of cell death." (PMID 33558496, 2021). "Our study represents a comprehensive pan-cancer analysis of LAMP2 and supports the potential use of the modulation of LAMP2 in the management of ESCA and various cancers." (PMID 35530327, 2022). "The results indicated that LAMP2 expression was significantly upregulated in ESCA and various human cancers." (PMID 35530327, 2022). "For example, LAMP2 gene expression levels were positively correlated with those of immunoinhibitors CD274 (PD-L1) and CSF1R in a variety of cancers." (PMID 35530327, 2022). "Anchoring HN3 to the membrane of the exosomes using LAMP2, made HN3LC9-293exo to specifically enter the GPC3+ HuH-7 cancer cells than the GPC3− LO2 cells in a co-culture model." (PMID 33062407, 2020). "LAMP1 and LAMP2 were expressed in the cytoplasm of cancer cells and inflammatory cells, whereas CDHR2 was only expressed in the cytoplasm of cancer cells." (PMID 31425520, 2019). "Additional Gal-9 interacting partners on other immune, non-immune, or cancer cell types include CD146, lysosome-associated membrane protein 2 (LAMP-2), and glucose transporter 2 (GLUT-2)." (PMID 40869319, 2025). "Furthermore, cisplatin-resistant cancer cells are characterized by reduction in the lysosomal compartment with downregulation of LAMP-1 and LAMP-2." (PMID 40277899, 2025).
cancer (continued). "We seek to know how metformin induces exosome biogenesis and secretion in cancer cells; and found that the mRNA level of genes related to exosome biogenesis and secretion such as Alix, Rab27b, CD81, CD63, and Lamp-2 concomitantly with CD63 protein level up-regulated in cells treated with metformin." (PMID 38627767, 2024). "Among them, LAMP1, LAMP2, LAMP4 and LAMP5 have been studied in relation to cancer and immunity." (PMID 38146591, 2024). "Liu’s pan-cancer analysis of 25 common tumors revealed that LAMP2 significantly impacted the tumor microenvironment (TME) of immune infiltration, for example, LAMP2 was positively correlated with T central memory cells, Th2 cells and natural killer cell, but negatively correlated with Th17 cells." (PMID 37986192, 2023). "Moreover, we retrieved LAMP2 in the HPA database for RNA expression in various tissues and pan cancers." (PMID 36741911, 2023). "In summary, we found that LAMP2 may have a role in predicting poor prognosis and relate to the level of immune infiltration in ESCA and other cancers." (PMID 35530327, 2022). "Expression of Lamp2 was decreased in both Panc02 and KPC1 sgSlc4a4 tumors compared to the sgNT controls, supporting our conclusion that Slc4a4 depletion in cancer cells is sufficient to mitigate the acidic pH of the TME in PDAC." (PMID 36522548, 2022). "None of the other cancer types showed any significant correlation (p > 0.05) between LAMP2 expression levels and tumor infiltration by immune cells." (PMID 35530327, 2022). "Future studies will need to unravel how cells coordinate the cholesterol transporter activities of NPC1, LAMP2 and LIMP2 when LDL-cholesterol supply is high and whether the cholesterol-binding activities of LAMPs and LIMP2 are relevant contributors to the pathophysiology of certain cancers." (PMID 35806209, 2022). "However, no previous studies have evaluated the significance of LAMP2 on a pan-cancer basis." (PMID 35530327, 2022). "Anchoring HN3 to the membrane of the EVs through LAMP2, drastically increased the specific homing of HLC9-EVs to GPC3+Huh-7 cancer cells rather than co-cultured GPC3−LO2 cells." (PMID 37202772, 2023). "Interestingly, cancer exosomes, but not normal exosomes, modulated expression of matrix remodelling (EFEMP1, DDK3, SPARC), cell cycle (EEF2K), membrane remodelling (LAMP2, SRPX), differentiation (SPRR2E), apoptosis (CTSC), transcription/translation (KLF6, PUS7)." (PMID 30008265, 2018).
infection (60 papers, 2009 to 2025). The state of being infected such as from the introduction of a foreign agent such as serum, vaccine, antigenic substance or organism. "To determine the fate of S. agalactiae after internalisation within the glia, we immunolabelled the cells at 24 h post infection for lysosome-associated membrane protein 2 (LAMP-2)." (PMID 35281448, 2022). "For this purpose, we analyzed and quantified the association of the late endosomal marker LAMP-2 to the phagosome containing the M. tuberculosis strains after 3 h of infection in J774 macrophages." (PMID 31782338, 2019). "Prior work had shown that exposure to toll-like receptor ligands, immune mediators often associated with infection, alters LAMP2 isoforms mRNA expression in human B lymphoblasts." (PMID 30211163, 2018). "During in vitro infection of macrophages, we observed a significantly increased association of the late endosomal marker LAMP-2 to MtΔmce2RComp-containing phagosomes as compared to MtΔmce2R and the wild type strains." (PMID 24007602, 2013). "The amount of LAMP-1 and LAMP-2 associated with E. coli phagosomes increased at each time-point over the first two hours, from a low immediately after infection to a high that was maintained between two and four hours after infection (ECOL)." (PMID 21426584, 2011). "Nevertheless, Western blotting analysis revealed that the protein level of p62 was increased while the protein level of Lamp2 was increased after GCRV-II infection, indicating that the autophagic flux was inhibited after GCRV-II infection." (PMID 40172227, 2025). "In infection with Mtr, gp82 interaction with Lamp2 triggers host cell actin remodelling and further lysosomal recruitment to the PM through induction of the PI3K pathway." (PMID 39611395, 2024). "The down-modulation of LAMP2 was associated with HIV latency, and the restoration of LAMP2 expression accompanied the transition of viral latency to active infection." (PMID 38750478, 2024). "An average of 50% of the counted intracellular bacteria were colocalized with LAMP-2 at the 60 and 90 min post-infection time points, which was significantly increased compared with the 7.5 min time point." (PMID 38722166, 2024). "Accordingly, we determined the colocalization status of R. montanensis, R. typhi, and R. rickettsii (SS) with LC3B and Lamp2 during infection of Beclin1fl/fl-LysM-Cre or Beclin1fl/fl (corresponding WT control) BMDMΦ by IFA." (PMID 37819111, 2023). "are ubiquitinated upon host cell entry, we next evaluated the status of autophagy marker, LC3B, and lysosomal marker, Lamp2, during infection of WT BMDMΦ by immunofluorescence assay (IFA)." (PMID 37819111, 2023). "The lysosomal protein LAMP2 was decreased after infection, but after NAC, was increased compared to the control group." (PMID 35178153, 2022). "Instead, EV71 was efficiently uncoated 30 min after infection in late endosomes (LEs) containing hSCARB2, mannose-6-phosphate receptor (M6PR), RAB9, bis(monoacylglycero)phosphate and lysosomal associated membrane protein 2 (LAMP2)." (PMID 35929543, 2022). "While wild-type C. burnetii generally established a single large LAMP-2 positive CCV per cell at 60 h post-infection, the ΔankG mutant infection produced multiple smaller LAMP-2 positive CCVs per cell." (PMID 35134097, 2022). "At 24 h post-infection, R. montanensis cells appear fragmented and co-localized with markers of lysosomal compartments, LAMP-2, and Cathepsin D, within PMA-differentiated THP-1 cells." (PMID 33669499, 2021). "Later on, LAMP-2+ BCVs progressively decreased and at 24 h after infection the majority of bacteria were enclosed within calnexin+ (endoplasmic reticulum marker) vacuoles and they remained positive for calnexin up to 48 h post-infection." (PMID 29963502, 2018). "The infected hMDMs were fixed at 2 h post-infection and labeled with antibodies specific for the late endosomal/lysosomal marker, LAMP2, and lysosomal enzyme, cathepsin D, and the ER marker, KDEL." (PMID 28321389, 2017).